TKTL1 (transketolase like 1)
Description:
Catalyzes the transfer of a two-carbon ketol group from a ketose donor to an aldose acceptor, via a covalent intermediate with the cofactor thiamine pyrophosphate (By similarity). Thus, catalyzes the reversible transfer of a two-carbon ketol group from sedoheptulose-7-phosphate to glyceraldehyde-3-phosphate, producing xylulose-5-phosphate and ribose-5-phosphate (By similarity). The phosphate group of the substrate plays a role in stabilizing the substrate-thiamine intermediate while preventing the formation of the reactive enamine intermediate (By similarity). Can also use fructose-6-phosphate as a ketose donor (By similarity). [Isoform 4]: During fetal neocortex development, may be essential to maintain the full number of basal radial glia (bRG). bRG are neural progenitor cells that undergo asymmetric divisions, generating a bRG (self-renewal) and a neuron, in contrast to basal intermediate progenitors (bIPs), which typically divide once to give rise to 2 neurons. bRG generate more cortical neurons over time than bIPs.
Synonyms: TKR; TKT2
Tractability: PROTAC: ubiquitination databases record sites on it; its protein half-life has been measured.
Gene: Protein-coding gene on chromosome X (154,295,795 to 154,330,350, forward strand). Ensembl gene ENSG00000007350.
Subcellular location: Cytoplasm
Subcellular location (Human Protein Atlas): Cytosol
Gene Ontology:
Molecular function: transketolase activity; thiamine pyrophosphate binding
Biological process: glucose catabolic process; thiamine metabolic process
Cellular component: cytosol; cytoplasm
Homologues: Orthologues: macaque TKTL1 (97% identical), chimpanzee TKTL1 (90% identical), dog TKTL1 (80% identical), pig TKTL1 (79% identical), guinea pig TKTL1 (75% identical), mouse Tktl1 (70% identical), rat Tktl1 (70% identical), rabbit TKTL1 (62% identical), Drosophila melanogaster CG8036 (54% identical), Caenorhabditis elegans tkt-1 (53% identical), Drosophila melanogaster CG5103 (49% identical). Paralogues in human: TKTL2 (73% identical), TKT (62% identical), PDHB (15% identical), BCKDHB (15% identical).
Diseases named in the same sentence as TKTL1 in open-access papers:
TKTL1 is named in the same sentence as 75 diseases in open-access papers, as found by Europe PMC text mining. Sharing a sentence is not in itself a finding about the gene and the disease. The quoted sentences say what the papers report.
colon carcinoma (12 papers, 2006 to 2024). "TKTL1 has been found to be associated with promoting lung cancer, colon cancer and urothelial cancer, cervical cancer, gastric cancer, and renal cancer." (PMID 38675412, 2024). "Enhanced expression of TKTL1 has recently been implicated in the conversion of cells to aerobic, glycolytic metabolism as well as increased proliferation in colon cancer cells." (PMID 19305507, 2009). "In colon cancer, increasing expression of TKTL1 has been associated with local progression at the primary tumor site (T1–2 versus T3–4) whereas patients presenting with distant metastasis (M1) had (primary) tumors expressing less TKTL1 than those of M0-patients." (PMID 30044385, 2018). "TKTL-1 was found to be up-regulated and correlated with cell progression and metastasis formation in colon cancer." (PMID 35887232, 2022). "This has been observed in human colon cancer cells, where inhibition of TKTL1 gene expression has led to a reduced proliferation rate and decreased glucose metabolization." (PMID 36009359, 2022). "An induction of TKTL1 by hypoxia has been described in T84 and Caco-2 cells, derived from a lung metastasis of human colon carcinoma and from a colon carcinoma, respectively." (PMID 30044385, 2018). "Consistent with these attributes, an increased expression of TKTL1 on the mRNA and/or protein level has been reported in several tumor entities, including glioblastoma and colon cancer." (PMID 30044385, 2018). "In the same study, five colon cancer samples have been analysed by quantitative PCR, also showing TKTL1 overexpression in invasive carcinomas on mRNA level." (PMID 21854597, 2011). "Shin and co-workers described an upregulation of glycolytic enzymes including Transketolase in 5-FU resistant colon cancer cell lines, an argument for the potential involvement of TKTL1 in progression and therapy resistance." (PMID 21854597, 2011). "TKTL1 expression in colon cancer was shown to be upregulated as compared to TKT and TKTL2 expression using immunohistochemistry and cell culture assays." (PMID 21854597, 2011). "Our previous study revealed that TKTL1 play an important role in cell proliferation of colon cancer, hepatoma and nasopharyngeal carcinoma." (PMID 19331662, 2009). "When comparing the transcript levels from five colon cancer tissues to nontumour samples from the same patients, we initially detected a 35-fold overexpression of TKTL1 in one colon carcinoma sample." (PMID 16465194, 2006). "In contrast, all invasive colon carcinomas showed TKTL1 expression, in particular, 20% were classified as weakly positive for TKTL1 (score 1+), 25% as positive (score 2+), and 55% as strongly positive (score 3+)." (PMID 16465194, 2006). "We found that in colon carcinomas and urothelial carcinomas, expression of TKTL1 transketolase correlated with invasiveness of tumours and poor patient survival." (PMID 16465194, 2006). "TKTL1, located on chromosome Xq28, is a regressive enzyme of the non-oxidized part of PPP that generates approximately 60–70% of TKT activity in human colon cancer and liver cells." (PMID 38675412, 2024). "Similar to bladder carcinomas, no or weak reactivity for TKTL1 was observed in noninvasive colon carcinomas, whereas in invasive tumours, strong TKTL1 staining was detected." (PMID 16465194, 2006). "Using these primers, a 79-fold overexpression of the TKTL1 gene was identified in one colon carcinoma tissue, whereas none of the tested colon carcinomas showed an overexpression of the TKT transcript." (PMID 16465194, 2006). "Non-neoplastic colon tissues examined did not reveal TKTL1 expression, and noninvasive colon cancer specimens were negative or barely positive for TKTL1 staining." (PMID 16465194, 2006). "Significant reduction in cell growth and viability in human LoVo and HCT116 colon cancer cells treated with TKTL1 siRNA as compared to LoVo/HCT116 cells without RNAi treatment in a cell culture model using quantitative PCR was demonstrated by two different groups." (PMID 21854597, 2011).
breast carcinoma (10 papers, 2006 to 2025). "We compared the potential diagnostic value of Apo10 and TKTL1 with commonly used tumor markers in differentiating breast cancer patients." (PMID 39644404, 2025). "Building on this foundation, in the present study, we further evaluated the combined detection of Apo10 and TKTL1 for potential use in early breast cancer screening, aiming to distinguish patients with early-stage disease from healthy individuals." (PMID 39644404, 2025). "Blood macrophage Apo10 and TKTL1 detection is a novel, noninvasive cancer screening approach, but its relevance in breast cancer remains uncertain." (PMID 39644404, 2025). "Among the numerous metabolic pathway-associated genes, the high expression of GLUT1, G6PD, TKTL1 and PGI/AMF are significantly correlated with decreased survival in breast cancer." (PMID 33723286, 2021). "To date, no studies have characterized the protein expression of TKT and TKTL1 and their potential role in the onset of canine mammary tumors." (PMID 28143530, 2017). "Földi indicated that TKTL1 expression in 86% of breast cancer specimens with 45% showing high expression levels." (PMID 19331662, 2009). "Furthermore, through a comparative analysis of the diagnostic efficacy of APT (Apo10 and TKTL1) with that of conventional markers, we discovered that APT’s sensitivity in detecting breast cancer surpassed that of other traditional tumor markers." (PMID 39644404, 2025). "However, the potential of Apo10 and TKTL1 for detecting early breast cancer remain to be further studied." (PMID 39644404, 2025). "In the early screening of breast cancer, Apo10 and TKTL1 exhibited unparalleled significance." (PMID 39644404, 2025). "The area under the ROC curve (AUROC) was calculated to compare the diagnostic efficiency of Apo10 and TKTL1 with conventional biomarkers (carcinoembryonic antigen [CEA], cancer antigens [CA-125, CA-199, CA-153]) in differentiating breast cancer from healthy breasts and benign breast nodules." (PMID 39644404, 2025). "Furthermore, the statistical analysis of different histological types showed an increased TKTL1 expression in hyperplastic lesions and in both benign and malignant simple tumors, in agreement with other reports in women breast cancer." (PMID 28143530, 2017). "TKT and TKTL1 protein expression was investigated by immunohistochemistry in canine normal (N = 6) and hyperplastic glands (N = 3), as well as in benign (N = 11) and malignant mammary tumors (N = 17)." (PMID 28143530, 2017). "In addition, over-expression of TKTL1 has since been validated as a potential biomarker and treatment target in breast cancer." (PMID 19305507, 2009). "We found that the Apo10, TKTL1, and APT levels in the breast cancer group were significantly greater than those in the benign breast nodule group and healthy control group." (PMID 39644404, 2025). "The results indicated that the Apo10, TKTL1, and APT levels in the breast cancer group were consistently and significantly different from those in both the breast nodule group and the healthy control group (P < 0.05)." (PMID 39644404, 2025). "HeLa, HEK293T, and breast cancer MCF7 cell growth was enhanced by CDH1 knockdown and TKTL1 overexpression, and exhibited inhibited growth after CDH1 overexpression and TKTL1 knockdown." (PMID 31175280, 2019). "We observed increased expression of TKT and TKTL1 in the proposed multistep carcinogenesis of CMT, thus indicating that PPP is a cancer metabolism-related pathway also in canine mammary tumors." (PMID 28143530, 2017). "Furthermore Apo10 and TKTL1 have been used prospectively for epitope detection in monocytes (EDIM)-blood test in patients with OSCC (n = 50), breast cancer (n = 48), prostate cancer (n = 115), and blood donors/controls (n = 74)." (PMID 24304513, 2013). "Fourth, blood levels of Apo10 and TKTL1 serve as pancancer markers and may not be exclusively elevated in patients with breast cancer." (PMID 39644404, 2025).
breast carcinoma (continued). "The AUROCs of APT, Apo10 and TKTL1 were greater than 87%, whereas the AUROCs of CEA, CA-125, CA-153, and CA-199 were only approximately 60%, indicating the diagnostic significance of APT in differentiating breast cancer from noncancerous conditions." (PMID 39644404, 2025). "Compared with conventional biomarkers, Apo10, TKTL1, and APT showed superior early-stage breast cancer screening efficacy, potentially emerging as a promising marker for discriminating breast cancer from healthy breasts and nontumoral lesions." (PMID 39644404, 2025). "Reactive bands were observed for TKTL1 at a slightly lower molecular weight (approx. 58 kDa) than TKT, with different signal intensities in normal and in mammary tumor tissues, as well as in the positive control; again, no signal was detected in the negative control." (PMID 28143530, 2017).
prostate carcinoma (9 papers, 2006 to 2026). A carcinoma that arises from epithelial cells of the prostate gland. "The overall sensitivity and specificity of serum TKTL1 levels in distinguishing oral squamous cell carcinoma patients, prostate cancer patients, and healthy controls were 90.6% and 95.9%, respectively." (PMID 39644404, 2025). "Studies have indicated that exosomal biomarkers, TKTL1, and UHRF1 are associated with the prognosis of prostate cancer and hold potential as tumor markers." (PMID 37838928, 2024). "Given these promising preclinical data, it was reasonable to offer the patient the option of co-treatment with B-OT, especially since TKTL1 expression is known to increase significantly during disease progression in prostate cancer patients." (PMID 39444815, 2024). "This is in agreement with previous findings, where elevated TKTL1 and Apo10 levels are correlated with the presence of prostate cancer and oral squamous cell carcinoma." (PMID 35864157, 2022). "SiRNA-mediated silencing reduced TKTL1 expression by 86 ± 13% in human PC-3S prostate cancer cells, by 81 ± 13% in human PC-3M prostate cancer cells and by 60 ± 28% in human HCT116 colorectal carcinoma cells (n = 5; p < 0.01 for all)." (PMID 27391434, 2016). "In patients with histologically confirmed OSCC, breast and prostate cancers, blood samples before surgery revealed significant elevated levels of Apo10 and TKTL1 in CD14/CD16 positive monocytes compared to blood donors." (PMID 24304513, 2013). "Furthermore, the sensitivity and specificity of the combined detection of serum Apo10 and TKTL1 levels in distinguishing oral squamous cell carcinoma patients, prostate cancer patients, and healthy controls were 95.8% and 97.3%, respectively." (PMID 39644404, 2025).
colorectal cancer (8 papers, 2008 to 2023). A primary or metastatic malignant neoplasm that affects the colon or rectum. "Subsequently, we screened four genes (ALOX15, GHRHR, TFPI2 and TKTL1) with aberrant methylation and aberrant hydroxymethylation at some genome position by functional enrichment analysis as candidate genes associated with colorectal cancer." (PMID 27546520, 2016). "In colorectal cancer tissues, TKTL1 was significantly upregulated, and correlated with liver metastases and poor disease-free survival." (PMID 35711845, 2022). "High levels of TKTL1 were also correlated with invasion and poor prognosis in urothelial, laryngeal squamous and colorectal cancer." (PMID 26907172, 2016). "Tumor tissues from 63 patients diagnosed with colorectal cancer at different stages of progression were analyzed for TKTL1 by immunohistochemistry." (PMID 21980427, 2011). "Our results provide evidence that TKTL1 expression in primary colorectal cancer is strongly correlated with tumor progression." (PMID 21980427, 2011). "Expression of TKTL1 was analyzed by immunohistochemistry in 63 patients with primary colorectal cancer (CRC)." (PMID 21980427, 2011). "Nevertheless, there is a need for more detailed study of the correlation of TKTL1 with tumor progression in colorectal cancer, to elucidate its role in lymph-node affection and metastasis." (PMID 21980427, 2011). "Here we present a new image analysis quantification method for the evaluation of immunostains that allow us to examine how TKTL1 expression varies with the progression stage in a series of colorectal carcinomas." (PMID 21980427, 2011). "As TKTL1 appears to be a valid biomarker for cancer prognosis, the aim of the current study was to correlate its expression with tumor stage, probability of tumor recurrence and survival, in a series of colorectal cancer patients." (PMID 21980427, 2011). "However, a recent study of a large cohort of colorectal cancer patients with liver metastases found that TKTL1 may serve as a reverse prognostic significance." (PMID 35711845, 2022). "Our RNA-Seq analysis also found that 5’-Aza-CdR exposure resulted in overexpression of multiple CT antigens in gastric cancer and colorectal cancer, including SSX1, TKTL1, SPANXB1, PNMA5, PNMA6E, GAGE12J, and PRSS56." (PMID 37400936, 2023).
melanoma (8 papers, 2016 to 2025). A malignant, usually aggressive tumor composed of atypical, neoplastic melanocytes. "Elevated TKTL1 expression enhanced the Warburg effect by accelerating glucose utilisation and lactate production and TKTL1 loss and gain of function studies revealed that TKTL1 enhanced invasion in melanoma cells." (PMID 26907172, 2016). "The present study evaluates the role of TKTL1 as a mediator of disease progression in melanoma associated with a defective methylation phenotype." (PMID 26907172, 2016). "We detected increased expression of TKTL1 in a subset of metastatic melanoma tumors and cell lines and found TKTL1 expression in melanoma tumors was associated with promoter hypomethylation." (PMID 26907172, 2016). "The functional significance of the increased TKTL1 in melanoma, its association with DNA hypomethylation and the Warburg effect has not previously been reported." (PMID 26907172, 2016). "Loss and gain of function studies revealed that TKTL1 contributed to enhanced invasion of melanoma cells." (PMID 26907172, 2016). "We found a significant association of hypomethylation with TKTL1 gene expression in melanoma patient samples." (PMID 26907172, 2016). "We extended our studies to a publically available clinical melanoma patient dataset to determine whether deregulation of TKTL1 expression was linked to DNA hypomethylation." (PMID 26907172, 2016). "Augmented expression of TKTL1 in melanoma cells was associated with a glycolytic phenotype." (PMID 26907172, 2016). "In agreement with other reports, we observed that increased TKTL1 resulted in accelerated glucose uptake and lactate secretion in melanoma cells and this was associated with changes in the proliferation and invasion in melanoma cells." (PMID 26907172, 2016). "To determine whether TKTL1 expression in melanoma was linked to the expression of CTAgs, we queried the TCGA database comprising of 261 melanoma patient samples." (PMID 26907172, 2016). "We speculate that in melanoma aberrant demethylation occurs as a common underlying mechanism that links transcriptional activation of TKTL1 and CTAgs that may cooperate to promote cancer progression by mechanisms such as Warburg effect, motility, proliferation and apoptosis." (PMID 26907172, 2016). "In melanoma, however, promoter hypomethylation results in the aberrant expression of TKTL1, promoting a glycolytic phenotype." (PMID 40573249, 2025). "It has been previously reported that hypomethylation of the TKTL1 promoter leads to overexpression of TKTL1 in melanoma and squamous cell carcinoma of the head and neck." (PMID 36009359, 2022). "TKTL1 was highly expressed in melanoma cells and promoted the invasion of melanoma cells.In our experiment, it was found that TKTL1 interference inhibited the proliferation, invasion and migration of CC cells and promoted cell apoptosis." (PMID 34922556, 2021). "The promoter methylation status of TKTL1 in melanoma cells was evaluated by quantitative methylation specific PCR." (PMID 26907172, 2016). "The TKTL1 promoter was activated by hypomethylation and treatment with 5aza induced TKTL1 expression in melanoma cells." (PMID 26907172, 2016). "Biochemical and molecular analyses such as glucose consumption, lactate production, invasion, proliferation and cell cycle progression together with ectopic expression and siRNA mediated knockdown were used to investigate the role of TKTL1 in melanoma cells." (PMID 26907172, 2016). "Here, we demonstrate that melanoma cells expressing TKTL1 are predominately glycolytic and that TKTL1 expression increases both cellular proliferation and invasion." (PMID 26907172, 2016). "To determine the role of TKTL1 in melanoma, we sought to manipulate TKTL1 levels in melanoma cell lines by siRNA-mediated knockdown and vector-mediated over-expression." (PMID 26907172, 2016). "This in turn points to the potential of targeting TKTL1-expressing melanomas particularly if they prove to be dependent on it for their survival." (PMID 26907172, 2016).